CRP (C-reactive protein)
Diseases named in the same sentence as CRP in open-access papers (continued):
Sharing a sentence is not in itself a finding about the gene and the disease.
fungal infections (continued). "C-reactive protein (CRP) is one such marker whose elevated serum levels are seen in acute Gram-positive, Gram-negative, and fungal infections." (PMID 23634180, 2013). "Moreover, the white blood cell (WBC) count and C-reactive protein (CRP) level may be normal or slightly changed in fungal infections, but the neonate reported in this study had significant increases in WBC and CRP." (PMID 33750330, 2021). "In the group with fungal infections, mean level of CRP was (11.31 ± 6.86) mg/dL; median level of PCT was 1.15 (interquartile range: 0.41‐10.22) ng/mL, while in the control group, mean level of CRP was (7.90 ± 6.44) mg/dL; median level of PCT was 0.34 (interquartile range: 0.12‐2.98) ng/mL." (PMID 31971308, 2020). "Other biomarkers, such as procalcitonin and CRP, can sometimes be misleading - procalcitonin may be negative in viral or fungal infections, and CRP is nonspecific and may rise due to another infectious or inflammatory event, not related to the well-being of the allograft." (PMID 40331298, 2025). "The results showed that decreased PaO2, increased CRP, increased LDH, increased CK, fungal infection, liver function damage, abnormal kidney function, and non-combined anticoagulation therapy were all independent risk factors for acute exacerbation (P < 0.05)." (PMID 41403446, 2025). "Logistic regression showed decreased PaO2, elevated CRP, LDH, and CK, fungal infection, abnormal liver/kidney function, and non-combined anticoagulation as independent acute-exacerbation risk factors." (PMID 41403446, 2025). "The CAPA group exhibited lower SaO2, PaO2, lymphocyte count, hemoglobin, albumin, and higher lactate, white blood cell count, neutrophil count, NLR, CRP, LDH, D-dimer and NT-proBNP compared to the group without fungal infection." (PMID 38263011, 2024). "Previous studies have found a correlation between CRP and Pneumocystis jirovecii in patients with non-HIV immunodeficiency, as well as a correlation between monocyte count and fungal infections." (PMID 38846353, 2024).
hypothyroidism (75 papers, 2007 to 2025). Abnormally low levels of thyroid hormone. "Tellechea showed, in a meta-analysis including 93 studies, that in patients with hypothyroidism, it was possible to risk-stratify the patients according to CRP concentration." (PMID 38714999, 2024). "On the other hand, our results suggest higher CRP after hypothyroidism in pregnancy combined with SIBO, suggesting an association with inflammation." (PMID 38628213, 2024). "CRP has been reported as a risk factor for hypothyroidism in cases with subacute thyroiditis, with a cutoff of 97.8 mg/L." (PMID 37873776, 2023). "The presence of a history of hypothyroidism and biomarkers (D-dimer, lactic dehydrogenase, CRP, and triglycerides) were associated with an increase in mortality in the studied cohort." (PMID 35628907, 2022). "A borderline association between CRP levels at first visit and hypothyroidism worsening was found (p = 0.066)." (PMID 34040018, 2021). "A borderline association between elevated CRP levels at first hospitalization and hypothyroidism worsening was found (p = 0.066)." (PMID 34040018, 2021). "The association between CRP levels in the first hospitalization and worsening of hypothyroidism had a borderline statistical significance (p = 0.066)." (PMID 34040018, 2021). "The association of hypothyroidism (both overt and subclinical) with increased C-reactive protein levels has also been reported." (PMID 33133591, 2020). "Our finding that CRP levels correlate to vascular TBRs during hypothyroidism seems to underline an inflammatory effect of hypothyroidism." (PMID 30859432, 2019). "Overt hypothyroidism is associated with elevated CRP levels." (PMID 40687584, 2025). "Additionally, CKD patients are at increased risk of hypothyroidism, likely due to hemodialysis, impaired iodine clearance, or inflammatory markers like CRP and IL-6, which cause endothelial damage and affect thyroid function." (PMID 39650928, 2024). "The data obtained in our study suggest that the presence of a history of hypothyroidism, a D-dimer ≥ 0.8 μg/mL, lactic dehydrogenase ≥ 430 IU/L, CRP ≥ 4.83 mg/dL, and triglycerides ≥ 214 mg/dL were associated with an increase in mortality in the studied cohort." (PMID 35628907, 2022). "Higher levels have been associated with a high CRP or BMI, hypothyroidism and steroid use." (PMID 31058118, 2019). "In addition, (subclinical) hypothyroidism has also been associated with increased systemic low-grade inflammation, as measured by elevated CRP and interleukin levels, compared to euthyroid patients." (PMID 30859432, 2019). "Other underlying mechanisms of CRP increase in both hyper- and hypothyroidism remain unclear." (PMID 24794233, 2014). "CRP levels increased in the hypothyroidism group, indicating the occurrence of a systemic inflammatory response and an elevated release of proinflammatory factors in pregnant women with hypothyroidism during pregnancy." (PMID 41573549, 2025). "TSH, TPOAb, CRP, percentage of Th17 cells, Th17/Treg ratio, IL-2, IL-6, IL-10 and TNFα levels increased significantly in the hypothyroidism group compared to the control group, and FT4 levels and percentage of Treg cells decreased significantly." (PMID 41573549, 2025). "Overt hypothyroidism can lead to lipid profile changes, causing altered LDL, B apolipoprotein, C-reactive protein (CRP), and homocysteine." (PMID 39507294, 2024). "Male gender, shift work, Helicobacter pylori infection, hypothyroidism, and elevated levels of VEGF, hs-CRP, and ESR are risk factors for CSC." (PMID 39347542, 2024). "Hypothyroidism patients had increased C-reactive protein (CRP), interleukin-2 (IL-2), IL-4, IL-10, and tumor necrosis factor (TNF)-α levels." (PMID 39185088, 2024). "In hypothyroidism, thyroid stimulation hormone (TSH) is favorably linked with glycated hemoglobin (HbA1c), triglyscride (TG), TyG index, BMI, WC, leptin, ANGPTL8, hs-CRP, and IR." (PMID 39252284, 2024).
hypothyroidism (continued). "In the present study, the serum CRP level was significantly increased in the hypothyroidism group, which is consistent with our previous findings." (PMID 37051293, 2023). "The proportion of participants with hypothyroidism was much higher in the high CRP group than in the low CRP group." (PMID 37686882, 2023). "Thyroid-stimulating hormone (TSH) and CRP levels were revealed to be risk factors for hypothyroidism in SAT patients, particularly in those with TSH levels less than 0.10 mIU/L and CRP levels greater than 97.80 mg/L." (PMID 37008914, 2023). "A 10-week zinc, vitamin A, and magnesium supplementation intervention increases serum-free T4 concentration and prevents the increase of serum CRP and malondialdehyde levels and body weight in adults with hypothyroidism." (PMID 37686882, 2023). "The proportion of participants with hypothyroidism was higher in the high-PRS than the low-PRS group within the low CRP group." (PMID 37686882, 2023). "In the adjusted Cox proportional hazards regression model, hypothyroidism, D-dimer ≥ 0.8 μg/mL, LHD ≥ 430 IU/L, CRP ≥ 4.83 ng/mL, and triglycerides ≥ 214 mg/dL were associated with an increased risk of death." (PMID 35628907, 2022). "In the Cox proportional hazard model, a history of hypothyroidism and biomarkers (D-dimer ≥ 0.8 μg/mL, lactic dehydrogenase ≥ 430 IU/L, CRP ≥ 4.83mg/dL, and triglycerides ≥ 214 mg/dL) were significantly associated with increased mortality." (PMID 35628907, 2022). "Only CRP was found to influence hypothyroidism worsening on multivariate analysis using backward logistic regression (p = 0.039), albeit with very little impact (OR 1.009, 95%CI 1.000–1.017)." (PMID 34040018, 2021). "In conclusion, as shown in this paper, the serum CRP concentration is increased in various types of hyperthyroidism and hypothyroidism." (PMID 24794233, 2014). "Hypothyroidism resulted in significant increases in the plasma inflammatory markers CRP and TNF-α and IL6, whereas reversing the hypothyroid state further increased these levels." (PMID 25333636, 2014). "The association of hypothyroidism with plasma pro-inflammatory markers such as TNF-α and CRP has been demonstrated in some studies." (PMID 25333636, 2014). "The results of our study demonstrated higher salivary CRP levels in SAT patients who presented with clinical features of hyperthyroidism when compared to HT patients who presented with clinical features of hypothyroidism and euthyroid control subjects." (PMID 21151525, 2010). "In subjects with sub-clinical hypothyroidism, CRP has been found to be positively related to insulin and higher than in control subjects with normal thyroid function." (PMID 19014658, 2008). "The higher CRP levels may indicate more severe inflammation that can damage the thyroid gland and result in hypothyroidism." (PMID 38715797, 2024). "C-reactive protein levels were higher in the hypothyroidism group than in the control group." (PMID 37051293, 2023). "A meta-analysis by Tellechea M.L. reported elevated CRP in patients with hypothyroidism." (PMID 38249164, 2023). "However, compared to the control group, higher serum CRP (p = 0.003) and TPOAb (p = 0.004) levels were observed in the hypothyroidism group." (PMID 37051293, 2023). "However, another study showed that hyperthyroidism cases have higher CRP than those with hypothyroidism or euthyroid, thus giving rise to further literature heterogeneities." (PMID 37873776, 2023). "Previous studies have shown different results on CRP levels in patients with hypothyroidism." (PMID 38249164, 2023). "There were 5 cases with creatine kinase elevations, 3 cases with creatine kinase isoenzymes, 2 cases of high troponin levels, 3 cases with different levels of interleukin −6 and the rise of hypersensitive c-reactive protein, and 1 case with subclinical hypothyroidism." (PMID 34765652, 2021). "This interaction results from the elevated CRP in hypothyroidism." (PMID 24794233, 2014).
hypothyroidism (continued). "In patients with hypothyroidism data on the level of CRP is contradictory." (PMID 22505888, 2012). "Hypothyroidism may result in inadequate protection to cells resulting in increased oxidative stress (OS), which in turn has been closely related to inflammation markers such as IL-6 and CRP." (PMID 38330593, 2024). "However, Western dietary patterns and MDA and CRP levels did not associate with an underactive thyroid." (PMID 37161471, 2023). "Identified cardiovascular risk factors include increased C-reactive protein, total cholesterol, low-density lipoprotein cholesterol (LDL-C), and decreased high-density lipoprotein cholesterol (HDL-C), all of which are also common in patients with hypothyroidism." (PMID 34463897, 2022). "The mechanism of CRP elevation in hypothyroidism is unknown." (PMID 24794233, 2014). "With respect to laboratory tests, they should be limited to a complete blood count, routine serum chemistries, thyroid-stimulating hormone (hypothyroidism may have symptoms similar to fibromyalgia or may accompany fibromyalgia) and erythrocyte sedimentation rate and/or C-reactive protein." (PMID 23213512, 2012). "We found that CRP, IL-2, IL-6 and TNF-α levels were increased in pregnant women with hypothyroidism in the first half of pregnancy." (PMID 41573549, 2025). "Studies have demonstrated that individuals with hypothyroidism exhibit elevated levels of proinflammatory cytokines, including TNF-α, IL-6, and C-reactive protein (CRP), when compared to healthy individuals." (PMID 39100850, 2024). "We found that the CRP, IL-2, IL-4, IL-10, and TNF-α levels were greater in the hypothyroidism group than in the control group." (PMID 39185088, 2024). "The serum CRP, IL-2, IL-4, IL-10 and TNF-α levels in the hypothyroidism group were greater than those in the control group (P < 0.05)." (PMID 39185088, 2024). "A retrospective study involving 95 Chinese patients with SAT found that patients with higher levels of C-reactive protein (CRP) and lower levels of thyroid-stimulating hormone (TSH) were more prone to developing hypothyroidism." (PMID 38715797, 2024). "In that study we observed that SAT occurring in the second and fourth quarter of 2020 were characterized by higher levels of FT4, CRP, Tg, and ESR and resulted in hypothyroidism in >80%." (PMID 36394704, 2023). "However, the serum CRP concentration did not influence hypothyroidism risk." (PMID 37686882, 2023). "In the adjusted Cox proportional hazards regression model, hypothyroidism, D-dimer ≥ 0.8 μg/mL, LDH ≥ 430 IU/L, CRP ≥ 4.83 ng/mL, and triglycerides ≥ 214 mg/dL were significantly associated with an increased risk of death." (PMID 35628907, 2022). "It is has been enough established that depressed patients exhibited elevated levels of C Reactive Protein (CRP) and a significant decrease in their Thyroid-stimulating hormone (TSH) levels, directly related with hypothyroidism." (PMID 32824737, 2020). "In another scientific report on patients with hypothyroidism and HT, the authors also showed significantly higher CRP levels compared to individuals without HT (p < 0.001)." (PMID 41439954, 2025). "A logistic regression model was constructed with gender, smoking history, alcohol consumption, obstructive sleep apnea, hypothyroidism, kidney disease, Helicobacter pylori infection, corticosteroid use, shift work, VEGF, hs-CRP, and ESR as independent variables and CSC as the dependent variable." (PMID 39347542, 2024). "C-reactive protein levels at treatment discontinuation were higher in patients who experienced SAT recurrence, while the coexistence of Hashimoto's thyroiditis was a significant predictive factor for the development of hypothyroidism." (PMID 38002783, 2023). "In patients who had worsening hypothyroidism, CRP levels were higher than in patients with no worsening (median 29.1 mg/L, 1.8–209.1 mg/L compared to median 9.9 mg/L, 0.6–288.9 mg/L, p = 0.066)." (PMID 34040018, 2021).
hypothyroidism (continued). "The age, gender, WBC, neutrophil count, ESR, CRP, thyroid function tests were similar in the groups that developed permanent hypothyroidism and that did not develop it (p > 0.05)." (PMID 32555998, 2020). "Concurrently, we found CRP levels to correlate to vascular TBRs, but not to vascular SUVs during hypothyroidism." (PMID 30859432, 2019). "In the study, the degree of elevation of CRP in plasma was not correlated with the severity of hypothyroidism." (PMID 24794233, 2014). "Some studies have detected elevated CRP in individuals with hypothyroidism, while others have not." (PMID 26100072, 2015). "However, CRP levels are not normalized by L-T4 administration in sub-clinical hypothyroidism and CRP is not related to TSH levels." (PMID 19014658, 2008). "In patients who had worsening in hypothyroidism, CRP levels were higher in the first hospitalization, with a median of 29.1 mg/L and a range of 1.8–209.1 mg/L compared to a median of 9.9 mg/L and a range of 0.6–288.9 mg/L in patients with no worsening in hypothyroidism." (PMID 34040018, 2021). "However, CRP is not a routinely measured parameter in the diagnosis of thyroid diseases, even though due attention should be given to it in the presence of thyroiditis, whether in the course of Hashimoto’s disease, hyperthyroidism or hypothyroidism induced by interferon (IFN)-α or amiodarone (AM)." (PMID 24794233, 2014).
preeclampsia (75 papers, 2006 to 2026). Preeclampsia is a hypertensive disorder of pregnancy that is characterized by new-onset hypertension with proteinuria presenting after 20 weeks of gestation, and depending on mild or severe forms may initially present with severe headache, visual disturbances, and hyperreflexia. "Inflammation and systemic immune response: Periodontal infections induce chronic systemic inflammation, increasing the production of pro-inflammatory cytokines (IL-6 and TNF-α) and CRP, which are also implicated in preeclampsia." (PMID 40496368, 2025). "Our team has previously shown that L-NAME administration increases circulating levels of factors associated with preeclampsia pathogenesis, including vasoconstrictor ET-1, anti-angiogenic factor sFLT-1, and marker of inflammation, CRP." (PMID 40362895, 2025). "The objective of this study was to assess the levels of CA-125, CRP and UA and to determine their association with preeclampsia in Sudanese pregnant women." (PMID 36689404, 2023). "This research aimed to evaluate the association of serum CA 125, CRP and uric acid with Preeclampsia." (PMID 36689404, 2023). "Other studies have also found high levels of CRP early in pregnancy to be associated with increased risk of preterm birth, as well as the risk of preeclampsia and growth restriction." (PMID 36130475, 2022). "For example, C-reactive protein (CRP) is associated with senescence of EPCs in preeclampsia patients." (PMID 25821786, 2015). "C-reactive protein (CRP) during pregnancy has been associated with adverse maternal outcomes such as preeclampsia and gestational diabetes mellitus." (PMID 26104503, 2015). "Further, CRP has been associated with oxidative stress and endothelial dysfunction, both of which are implicated in the development of preeclampsia." (PMID 26104503, 2015). "This study also reports an association between CRP and markers of vascular and organ damage in severe preeclampsia." (PMID 26113950, 2015). "Another study published recently showed that serum procalcitonin, CRP and D-dimer was significantly associated with preeclampsia." (PMID 24006912, 2013). "Among pregnant women, elevated CRP levels have been associated with adverse outcomes such as preterm delivery, preeclampsia, and fetal growth restriction." (PMID 22306530, 2012). "CRP has been associated with adverse pregnancy outcomes, including preterm delivery, preeclampsia, and intrauterine growth restriction." (PMID 20379412, 2009). "For example, analyzing and monitoring levels of leptin, adiponectin, FT4, insulin and CRP could assist in early identification of women at risk for preeclampsia or development of GDM." (PMID 36520252, 2023). "Preeclampsia is associated with significantly increased levels of vasoconstrictor endothelin-1 (ET-1), anti-angiogenic factor sFlt-1, and inflammatory marker C-reactive protein (CRP) in the maternal circulation, which are thought to contribute to systemic vascular dysfunction." (PMID 35897759, 2022). "CRP is an inflammatory biomarker that increases in oxidative stress and its higher levels are associated with a greater incidence of pregnancy complications such as preterm birth and preeclampsia." (PMID 33671070, 2021). "Serum CRP may predict preeclampsia, and may be a risk marker for preterm birth, perhaps by reflecting intrauterine infection." (PMID 31469064, 2019). "The association of CRP with disease severity in preeclampsia has been reported by other authors." (PMID 26113950, 2015). "Higher maternal levels of CRP are associated with preeclampsia and growth-restricted baby." (PMID 24659848, 2014). "The study suggested that CRP levels can be correlated with the process of development of preeclampsia." (PMID 39280386, 2024). "One objective and sensitive marker of the body's total inflammatory activity is CRP, which has been proposed as a potential sign of preeclampsia." (PMID 39280386, 2024).